ANGPT1 (angiopoietin 1)
Diseases named in the same sentence as ANGPT1 in open-access papers (continued):
Sharing a sentence is not in itself a finding about the gene and the disease.
glioma (13 papers, 2010 to 2022). A benign or malignant brain and spinal cord tumor that arises from glial cells (astrocytes, oligodendrocytes, ependymal cells). "In our study, ANGPT1 was one of the main serum proteins that helped to distinguish healthy subjects from glioma patients." (PMID 31861636, 2019). "The decision tree analysis indicates that serums ANGPT1, TIMP1, IP10, and TGFβ1 are promising combinations of targets for glioma diagnostic applications." (PMID 31861636, 2019). "In contrast, genes encoding angiogenic factors (ANGPT1, ANGPT2) and receptors (NRP1, and KDR) were highly expressed in SA-culture-derived glioma cells of 51B." (PMID 29113349, 2017). "Recently, several researchers found that some cytokines overexpressed in glioma cells after BV treatment contribute to angiogenesis, including platelet-derived growth factor, fibroblast growth factor, interleukin-8 and -10, and angiopoietin-1." (PMID 28005980, 2016). "Angiopoietin-1 (Ang-1), a Tie2 ligand, is likely to promote the recruitment of TEMs to tumor vasculature before the turn-on of the angiogenic switch in early stages of N202 breast carcinoma, Rip1-Tag2 pancreatic insulinoma and U87 human glioma." (PMID 31474975, 2019). "In this study, we sought to determine whether the angiopoietin 1 (Ang1)/Tie2 axis regulates crosstalk between glioma cells and endothelial cells." (PMID 21321379, 2010). "Depending on its function, ANGPT1 could be a molecular marker of glioma malignancy." (PMID 31861636, 2019). "Of these proteins, angiopoietin-1 is involved in vessel stabilization and modulating aberrant vessel development in GBM, while thrombospondin-1 has a role in angiogenesis and is overexpressed in high-grade gliomas, where it modulates expansion and invasion." (PMID 34641541, 2021). "In the RMPAlow gliomas, a different set of RTK signaling-related genes including MET (8.9%), EPHA1 (8.9%), EPHB6 (8.9%), EPHB4 (8.3%), BRAF (8.9%), FGF6 (11.9%), FGF23 (11.9%), NTF3 (11.9%), and ANGPT1 (9.5%) were amplified." (PMID 27385209, 2016). "In order to explore whether this contradiction exists in gliomas, we compared the expression levels of vascular stability-related markers (ANGPT1, ANGPT2, JAM2, MCAM, PDGFRB, and VE-Cadherin) in the high- and low-score glioma groups in the TCGA, CGGA, and CGGA (array) datasets." (PMID 35579998, 2022). "Therefore, an examination of the regulatory effects of BMAL1 on the expression of the angiogenic factors ANG1 (Angiopoietin 1), ANG2, and VEGF in glioma will be conducive to understanding the reasons for glioma tolerance to vascular targeted therapy and the development of new target drugs." (PMID 34815366, 2021). "Pre-treatment with C646 significantly reduced the enrichment of genomic sites in CDH5 and ANGPT1, but not the housekeeping gene RPL30 in radiated cells, thus confirming that P300 HAT activity is essential for radiation stress-induced epigenetic rewiring in glioma cells." (PMID 36261421, 2022).
liver fibrosis (13 papers, 2013 to 2022). "HSCs are also able to participate in angiogenesis, a pathophysiological process closely associated with liver fibrosis, by secreting proangiogenic cytokines, such as angiopoietin 1 (Ang1) and VEGF." (PMID 28890699, 2017). "It is noteworthy that activated HSCs secrete VEGF and angiopoietin-1 to promote angiogenesis in the model of murine liver fibrosis or exposure to leptin." (PMID 29156788, 2017). "The same group also showed that S1P induced the expression of angiopoietin 1 mRNA through S1P receptors 1 and 3 in hepatic stellate cells in liver fibrosis mouse models." (PMID 29208982, 2017). "Inflammatory mediators cause HSCs to differentiate into myofibroblasts and play a role in angiogenesis by releasing proangiogenic mediators, VEGF, and angiopoietin-1 during the development of liver fibrosis." (PMID 24023685, 2013). "They play a role in angiogenesis and act by releasing the proangiogenic mediators VEGF and angiopoietin-1 during the development of liver fibrosis." (PMID 24023685, 2013). "Other reports indicate that hepatic stellate cells, tissue-specific pericytes in the liver, overexpress FAP following activation and promote angiogenesis in liver fibrosis and hepatocellular carcinoma by increasing the levels of Angiopoietin-1 and Angiopoietin-2." (PMID 34282761, 2021). "Moreover, VEGF and angiopoietin-1, produced by activated HSCs, have been shown to trigger angiogenesis in a murine model with liver fibrosis or following exposure to leptin." (PMID 31455001, 2019). "The mRNA levels of angiogenesis markers, including Angpt1, CD31, and VCAM-1, were also markedly upregulated in the damaged liver, which was consistent with the progression of liver fibrosis." (PMID 30901579, 2019). "Based on the link between serum angiopoietin-1 and 2 levels and CHC progression, we aimed to determine the value of these angiogenic factors as noninvasive biomarkers of liver fibrosis." (PMID 23823085, 2013). "In the microenvironment of liver fibrosis with hepatic vasculature and tissue hypoxia alterations, HSCs produce multiple angiogenic factors, including vascular endothelial growth factor (VEGF), PDGF-BB, and angiopoietin 1 or 2, and express angiopoietin 1 receptors." (PMID 24927147, 2014). "We could observe a obvious up-regulation of angiopoietin-1 in hepatic fibrosis group compared with control group and bevacizumab did not lead to a down-regulation of angiopoietin-1 in fibrosis liver." (PMID 24023685, 2013).
colorectal cancer (11 papers, 2002 to 2024). A primary or metastatic malignant neoplasm that affects the colon or rectum. "Conversely, angiopoietin-1 is an apoptosis survival factor, and its deficiency affects the growth of colorectal cancer liver metastasis." (PMID 37208732, 2023). "SNPs of the ANGPT1 gene have been associated with the risk of autoimmune diseases, juvenile idiopathic arthritis, and portopulmonary hypertension, and also with the risk and clinical outcome of colorectal cancer (rs1954727)." (PMID 33573134, 2021). "We demonstrated a significant differential expression of VEGF-A and ANGPT-1 in colorectal cancer patients exhibiting the EMAST+ phenotype." (PMID 38719941, 2024). "Besides, upregulated ANGPT1 and downregulated COl11A1 are related to a better prognosis in lung cancer metastasis and proliferation in colorectal cancer." (PMID 32093414, 2020). "Our results suggest that angiopoietin-1 is an important mediator of angiogenesis and vascular permeability and thus could theoretically serve as an anti-neoplastic agent for patients with carcinomatosis from colorectal cancer." (PMID 12402160, 2002). "The mean values of RQ for VEGF-A was discovered to be higher in patients with stage III/IV colorectal cancer (P-value = 0.001), but no statistically significant differential expression was identified between ANGPT-1 and ANGPT-2 expression and tumor stage." (PMID 38719941, 2024). "ANGPT-1, ANGPT-2, and VEGF-A expression in colorectal cancer datasets." (PMID 38719941, 2024). "In colorectal cancer, reverse effects of ANGPT1 have been detected: ANGPT1 overexpression in combination with VEGF seems to induce angiogenesis whereas ANGPT1 alone seems to exert an anti-angiogenic effect by stabilizing the existing vasculature, and thus reducing any remodelling effects." (PMID 26044849, 2015).
Hypertension (11 papers, 2012 to 2025). The presence of chronic increased pressure in the systemic arterial system. "Circulating angiopoietin-2 levels are elevated in individuals with systemic hypertension and angiopoietin-1/angiopoietin-2 ratios are reduced in pregnant women who develop preeclampsia." (PMID 30234375, 2018). "We determined the expression of Cxcl12, Vcam1, Scf (Kitl) and Angpt1, thus sampling the canonical factors supplied by various niche cells to promote HSPC retention and quiescence in steady state that decline after acute MI37 in mice with hypertension or atherosclerosis." (PMID 35747128, 2022).
angioedema (10 papers, 2018 to 2025). Swelling involving the deep dermis, subcutaneous, or submucosal tissues, representing localized edema. "This category includes angioedema due to the mutation of angiopoietin-1 (HAE-ANGPT1), myoferlin (HAE-MYOF), and heparan sulfate-glucosamine 3-O sulfotransfersase (HAE-HS3ST6), which are structural endothelial proteins that bind kininogen." (PMID 40426779, 2025). "Recently, ANG-1 has also gained attention among HAE experts as a missense mutation of the ANGPT1 gene, leading to a reduced ability of the ANG-1 protein to bind Tie-2, was found to be associated with a new type of hereditary angioedema, named ANGPT1-HAE." (PMID 33725263, 2021). "Targeted re-sequencing of five HAE-associated genes (SERPING1, F12, PLG, ANGPT1, and KNG1) was performed in 212 ACEi/ARB-induced angioedema patients recruited in Germany/Austria, Sweden, and Denmark, and in 352 controls from a German cohort." (PMID 35923707, 2022). "In addition, the ANGPT2/ANGPT1 ratio (an index of vascular permeability) was decreased during angioedema attacks." (PMID 38829492, 2024). "Genetic testing of angioedema is primarily focused on detecting alterations in the DNA of genes encoding proteins that are part of the complement, fibrinolysis, coagulation, kinin, and vasculature systems, including C1-INH (SERPING1), FXII (F12), plasminogen (PLG), or angiopoietin-1 (ANGPT1)." (PMID 33560480, 2021). "These questions may indicate that BK-mediated angioedema comprises a heterogeneous group of multifactorial diseases, even if their pathomechanism can be linked to mutations of a single gene (SERPING1, FXII, ANGPT1, etc." (PMID 33725263, 2021). "Apart from these cases, hereditary angioedema is explained by other genetical defects affecting factor XII, angiopoietin-1, plasminogen, and kininogen 1 genes." (PMID 40599632, 2025). "In conclusion, the present analyses identified no known disease-causing HAE variant in SERPING1, F12, PLG, ANGPT1, or KNG1 in a cohort of around 200 patients with ACEi/ARB-induced angioedema." (PMID 35923707, 2022).
atherosclerosis (9 papers, 2017 to 2025). A disease characterized by the build-up of fatty material and calcium deposition in the arterial wall resulting in partial or complete occlusion of the arterial lumen. "Dysregulation of Angpt1 and Angpt2 expressions by Rgp are also linked to progression of atherosclerosis." (PMID 36250046, 2022). "Rgp increases the expression of Angpt2 while decreasing the expression of Angpt1 in human aortic smooth muscle cells, inducing their migration, a crucial event in the pathophysiology of atherosclerosis." (PMID 36250046, 2022). "However, it has been suggested in atherosclerosis that ANGPT1/Tie2 playanti-angiogenic, anti-inflammatory, and anti-atherogenic roles.Several studies have revealed that the functions of ANGPT1 and ANGPT2 inatherosclerosis are complex and paradoxical." (PMID 39076698, 2023). "Studies from our group and others have revealed that angiopoietin-1, pregnancy-associated plasma protein-A, and homocysteine inhibit ABCA1- and ABCG1-dependent cholesterol efflux from lipid-loaded macrophages and aggravate atherosclerosis in apoE−/− mice by downregulating LXRα expression." (PMID 33692340, 2021). "Third, we know that ANGPT1 is likely not the only mediator of sGC effects on atherosclerosis." (PMID 37484062, 2022).
hereditary angioedema (9 papers, 2018 to 2024). Hereditary angioedema (HAE) is a genetic disease characterized by the occurrence of transitory and recurrent subcutaneous and/or submucosal edemas resulting in swelling and/or abdominal pain. "Interestingly, variants in angiopoietins 1 gene (ANGPT1) are associated with a recently described form of hereditary angioedema (HAE)." (PMID 30083168, 2018). "The group will then develop pathogenicity classification rules to curate variants in genes responsible for Hereditary Angioedema with normal C1-INH (nl-C1-INH-HAE), such as F12, PLG, ANGPT1, KNG1, MYOF, and HS3ST6 (OMIM: 610618, 619360, 619361, 619363, 619366, 619367)." (PMID 38124188, 2023). "Hereditary angioedema due to C1 Inhibitor deficiency shares a common kinin dependency with other HAE situations: F12-HAE, PLG-HAE, KNG1-HAE, ANGPT1-HAE, and HS3ST6-HAE, but not with MYOF-HAE, U-HAE." (PMID 35958943, 2022).
ischemic stroke (9 papers, 2014 to 2024). A stroke disorder caused by obstruction of blood flow to the brain, due to thrombotic (local blood clot formation) or embolic (due to a blood clot or other material traveling from another site) event. "Another study found that ANGPT1 could be a diagnostic biomarker for ischemic stroke (IS)." (PMID 37409018, 2023). "Animal studies suggest that the expression of the protein angiopoietin-1 (angpt-1) alters following an ischemic stroke, and that upregulating angpt-1 reduces the severity of cerebral infarction." (PMID 36333663, 2022). "A previous study found that circulating angiopoietin-1 (angpt-1) concentrations were significantly lower in patients who had a recent ischaemic stroke compared to healthy controls." (PMID 36333663, 2022). "Studies showed that BHD could promote angiogenesis through increasing the expression of VEGF, VEGFR2, Flk-1, bFGF, and angiopoietin-1 (Ang-1) in ischemic stroke models both in vivo and in vitro." (PMID 31178960, 2019).
leukemia (9 papers, 2014 to 2025). A malignant (clonal) hematologic disorder, involving hematopoietic stem cells and characterized by the presence of primitive or atypical myeloid or lymphoid cells in the bone marrow and the blood. "With ongoing or chronic stress, such as in mice with leukemia, most stromal cell populations are diminished, with loss of expression of quiescence-promoting genes (Cxcl12, Angpt1, Vcam1) in Lepr+ AdipoCAR cells." (PMID 34368155, 2021). "Angiopoietins, particularly Angiopoietin-1 (Ang-1) and Angiopoietin-2 (Ang-2), are critical regulators of vascular remodeling and angiogenesis, including leukemia-induced angiogenesis." (PMID 40806429, 2025). "In the same way, we observed that leukaemia‐derived sEVs downregulated the expression of various genes (CXCL12, ANGPT1, COL1A1 and SCF) in BM‐MSCs, vital to maintaining normal haematopoiesis in BMM." (PMID 38499475, 2024). "For instance, genes like ANGPT1, PES1, and ZNF222 demonstrated promoter active demethylation by both compounds and are known for promoting cell survival and proliferation of different types of leukemia." (PMID 41516186, 2025). "Loss of normal hematopoiesis is a classical event during human myeloproliferative neoplasias and leukemias where the niche downregulate essential HSPC retention factors as CXCL12, SCF, LepR, Angpt1, Cdh2, Slit2, and TGF-β1 though pro-inflammatory factors secreted by leukemia-initiating cells." (PMID 28111575, 2016). "Furthermore, cryptic genomic alterations involving leukemia-related genes, such as ATP2B2, ANGPT1, ETV6 and RB1CC1, were inferred in the level of array CGH and confirmed by FISH." (PMID 25120648, 2014).
melanoma (9 papers, 2017 to 2025). A malignant, usually aggressive tumor composed of atypical, neoplastic melanocytes. "In addition, angiopoietin-1 deficient mice exhibited a significant increase in lung metastasis of B16F10 melanoma cells, compared to wild type mice 3 weeks after injection." (PMID 28800750, 2017). "ANGPT1 is significantly overexpressed in the vasculature of most tumors, and in ANGPT-1-deficient mice, MT-ret and B16F10 melanomas grow more slowly." (PMID 39866233, 2025). "Furthermore, we utilized B16F10 melanoma cells subcutaneous and experimental lung metastasis models in Angiopoietin-1 and Tek knockout mice." (PMID 28800750, 2017). "Population-specific patterns are also evident, such as increased Angiopoietin-1 (Ang-1) and granulocyte colony-stimulating factor (G-CSF) in US studies, and markedly higher CD163—a macrophage activation marker linked to immune suppression—in Japanese melanoma patients with irAEs." (PMID 40722787, 2025). "Furthermore, several vascular regulators reduced in SHP2-silenced mouse B16F10 cells and tumors were expressed at significantly higher levels in metastatic compared with primary human melanomas, including ANGPT1, THSB2 (codes for thrombospondin 2), PTX3, FGF7 (also known as KGF), and VEGFA." (PMID 40131370, 2025). "The balance between ANGPT1 and ANGPT2 undergoes a proangiogenic shift in melanoma." (PMID 39866233, 2025). "We found that primary tumor growth is not affected in Angpt1 deficient mice utilizing both the spontaneous MMTV-PyMT mammary tumor model and subcutaneous flank injections of B16F10 melanoma cells." (PMID 28800750, 2017). "To investigate this we performed in vitro experiments of the attachment of B16F10 melanoma cells to endothelial cells (HUVEC) with and without Angpt1 present." (PMID 28800750, 2017). "However, high or low expression of ANGPT1, PDGFA, and FGF2 has no impact on the survival probability of patients with primary melanoma." (PMID 34102002, 2021).
Obesity (9 papers, 2014 to 2025). Accumulation of substantial excess body fat. "Angiogenesis markers, such as angiopoietin 1 (Angpt1) and thrombospondin 1 (Thbs1), are associated with obesity." (PMID 36293486, 2022). "Additionally, treatment with ANGPT1 reduces the risk of diet-induced obesity." (PMID 39858399, 2024). "The proangiogenic factor ANGPT1 was expressed at a higher mRNA level in LL-Br compared to HF-Br, which is compatible with the known impairment of angiogenesis in obesity." (PMID 29695257, 2018). "In conclusion, a combination of upregulated obesity-related CVRPs (ANGPT1, IL, 1Ra, XCL1) and downregulated cardioprotective proteins (sRAGE, BMP6, Mn-SOD, GDF2) in PCOS may contribute to the increased risk of CVDs in overweight women with PCOS." (PMID 39858399, 2024). "Interestingly, as hypoxia is associated with obesity, angiogenesis marker ANGPT1 (angiopoietin 1) correlates positively with adipocyte size and body mass index-standard deviation score (BMI-SDS), a measure to define childhood obesity." (PMID 38483771, 2024). "Accordingly, we found that genes related to angiogenesis (e.g., ANGPT1, ANXA2), as well as to TGFβ signaling (e.g., SMAD4, BMPER, AKT2) are modulated in obesity condition." (PMID 30838002, 2019). "Interestingly, the expressions of CXCL-12 and Angiopoietin-1 were not reduced by the onset of obesity." (PMID 24595332, 2014).
glioblastoma (8 papers, 2011 to 2024). The most malignant astrocytic tumor (WHO grade IV). "The significantly higher expression of ANGPT1 was detected in the T98G glioblastoma cell line (2.20 compared to HDFa; 2.48 compared to hRNA; 27.98 compared to NHA; and 5.48 compared to all controls) and the SW1088 cell line compared to the NHA control (16.96)." (PMID 36142793, 2022). "In the case of glioblastoma multiforme, it appears that tumor cell-derived angiopoietin-1 is an absolute requirement for normalization." (PMID 26756205, 2016). "Recent studies show that AEG-1 is induced by hypoxia and glucose deprivation in glioblastoma, activates angiopoietin-1 (Ang1), matrix metalloproteinase (MMP)-2, and HIF-1, and plays a critical role in hepatocellular carcinoma progression as a target of microRNA-375." (PMID 23243443, 2012). "In particular, ANGPT1 has a role in the pathological vascularization of malignant astrocytomas and the balance between ANGPT1 and ANGPT2 has prognostic value in patients with primary glioblastoma multiforme." (PMID 21726470, 2011). "In total mRNA expression of TIMP-1, ANGPT1, SPP1, TGF-β1 and YKL-40 genes was analysed in 61 patients with different grade astrocytoma: 20 grade II diffuse astrocytoma, and 41 grade IV astrocytoma (glioblastoma), and in case of IP-10—in 11 grade II diffuse astrocytoma, and 24 glioblastoma samples." (PMID 34162919, 2021).